JMJD6 (jumonji domain containing 6, arginine demethylase and lysine hydroxylase)
Diseases named in the same sentence as JMJD6 in open-access papers (continued):
Sharing a sentence is not in itself a finding about the gene and the disease.
melanoma (20 papers, 2017 to 2025). A malignant, usually aggressive tumor composed of atypical, neoplastic melanocytes. "In the same study, increased JMJD6 expression was associated with more aggressive disease and with worse survival in melanoma patients." (PMID 31748572, 2019). "As expected from its role in splicing decisions, deregulation of JMJD6 function has important consequences on human health, and JMJD6 has been recently implicated in melanoma carcinogenesis through regulation of the alternative splicing of PAK1, a key MAPK signaling component." (PMID 30319972, 2018). "The overexpression of JMJD6 has been validated in different cancers, including neuroblastoma and melanoma." (PMID 38166895, 2024). "High expression of JMJD6 was closely related to advanced clinicopathologic stage, strong invasiveness and poor prognosis of melanoma." (PMID 37488513, 2023). "JMJD6 deficiency attenuated the growth of both Lewis lung carcinoma (LLC) tumors and B16F10 melanomas by reversing M2-like activation of macrophages, and sensitized tumors to immune checkpoint blockades (ICBs)." (PMID 37567973, 2023). "We treated melanoma-bearing WT and Jmjd6+/− mice with in vivo anti-mouse PD-1 McAb once every 3 days from the third day of tumor inoculation." (PMID 37567973, 2023). "It has been reported that two Ras-induced microRNAs (miR-146a and 193a) target JmjD6 in animals, thereby inducing down-regulation of its mRNA and protein levels at the onset of Ras expression during melanoma development." (PMID 35449230, 2022). "Our data on JMJD6 in PCa is consistent with involvement of JMJD6 in oral, breast, neuroblastomas, melanoma and ovarian cancers." (PMID 33925994, 2021). "JMJD6 facilitates proliferation and invasion of melanoma cells in vitro, and promotes growth and metastasis of melanoma in vivo." (PMID 31961032, 2020). "We first validated the on-target gene editing effects of Brd9&Jmjd6 and Kat6a&Jmjd6 dual-crRNAs in RN2c12 and B16-F10c12 melanoma cells." (PMID 32661245, 2020). "The website reported medium (in three patients) or high (in nine patients) nuclear JMJD6 immunostaining in malignant melanoma." (PMID 30619488, 2018). "As two of these microRNAs target Jmjd6 we investigated the significance of these interactions for melanoma progression." (PMID 30619488, 2018). "To our surprise we discovered that the target of these increased microRNAs, Jmjd6, is overexpressed in aggressive zebrafish melanoma." (PMID 30619488, 2018). "Given the dynamic changes in Jmjd6 expression in the Ras-induced melanoma model in zebrafish, and the overall increase in expression in human melanoma, we wanted to clarify the role of Jmjd6 in melanoma with a gain of function approach." (PMID 30619488, 2018). "Increased JMJD6 expression is found in several human cancers, including melanoma, suggesting that the up-regulation of Jmjd6 is a critical event in tumor progression." (PMID 30619488, 2018). "This suggested that overexpression of Jmjd6 promotes melanoma progression and that the increase of the microRNAs that downregulate Jmjd6 at the onset of Ras expression is part of a defensive response against the pro-oncogenic activity of Jmjd6." (PMID 30619488, 2018). "It is intriguing that one of the microRNAs targeting Jmjd6 in this progressive model of melanoma is miR-146a, a well-known regulator of inflammatory responses." (PMID 30619488, 2018). "We found that JMJD6 is upregulated in different cancers, with melanoma being one of the cancer having higher levels of JMJD6 expression and high genomic alteration frequency (with amplification in almost 3% of cases)." (PMID 30619488, 2018). "We were puzzled by the massive presence of L-plastin positive cells (leukocytes, possibly including neutrophils and macrophages) within the kita/Ras/Jmjd6 melanomas, compared to kita/Ras melanomas." (PMID 30619488, 2018).
melanoma (continued). "At later stages of melanoma development, and in human malignant melanoma with unfavorable prognosis, Jmjd6 is overexpressed, and in a zebrafish model where melanocytes express both Ras and Jmjd6, melanomas are more aggressive." (PMID 30619488, 2018). "Two Ras-induced microRNAs (miR-146a and 193a) target Jmjd6, inducing downregulation of its mRNA and protein levels at the onset of Ras expression during melanoma development." (PMID 30619488, 2018). "Next, we investigated the levels of JMJD6 protein in human melanoma using the website Protein Atlas7." (PMID 30619488, 2018). "The finding that both microRNAs target Jmjd6 and that this regulation is conserved in zebrafish and human melanoma suggests that lowering JMJD6 levels in cancer is another function of the tumor suppressors miR-146a and miR-193a." (PMID 30619488, 2018). "Next, we analyzed the expression levels of JMJD6 in different types of cancers, including melanoma, using the website cBioPortal for Cancer Genomics6." (PMID 30619488, 2018). "Results reported here indicate that Jmjd6 is a critical player in zebrafish melanoma development and that at least two Ras-induced microRNAs antagonize Jmjd6 activation." (PMID 30619488, 2018). "We found that high expression of JMJD6 is closely correlated with advanced clinicopathologic stage, aggressiveness, and poor prognosis of melanoma." (PMID 29187213, 2017). "We demonstrated that JMJD6 is transcriptionally activated by c-Jun, generating a feedforward loop to drive the development and progression of melanoma." (PMID 29187213, 2017). "In the current study, we demonstrated that JMJD6 promotes EMT and metastasis in melanoma, and we showed that JMJD6 does so, through its lysyl hydroxylase activity and via its regulation of the alternative splicing of PAK1." (PMID 29187213, 2017). "Meanwhile, the level of the exon-skipped PAK1 mRNA isoforms, PAK1Δ15, was significantly elevated in JMJD6-depleted melanoma cells." (PMID 29187213, 2017). "Here we report that the jumonji C domain-containing demethylase/hydroxylase JMJD6 is markedly up-regulated in melanoma." (PMID 29187213, 2017). "To further explore the functional significance of the regulation of the alternative splicing of PAK1 by JMJD6 and to substantiate the role of JMJD6 in melanoma carcinogenesis, we next investigated the effect of JMJD6 on the proliferation of melanoma cells." (PMID 29187213, 2017). "In support of the regulation of PAK1 thus the MAPK signaling by JMJD6, our experiments also revealed that JMJD6 regulates melanogenesis and angiogenesis in melanoma cells." (PMID 29187213, 2017). "Collectively, these findings suggest that JMJD6 plays an important role in the development and progression of melanoma." (PMID 29187213, 2017). "Our results indicate that JMJD6 is critically involved in melanoma carcinogenesis, supporting the pursuit of JMJD6 as a potential biomarker for melanoma aggressiveness and a target for melanoma intervention." (PMID 29187213, 2017). "To investigate the role of JMJD6 in melanoma carcinogenesis, we first detected JMJD6 expression in melanomas by tissue array." (PMID 29187213, 2017). "These experiments are consistent with in vitro observations and indicate that JMJD6 promotes the growth and metastasis of melanoma in vivo." (PMID 29187213, 2017). "We then infected B16F10 cells, a melanin-producing mouse melanoma cell line, with lentiviruses carrying control shRNA or Jmjd6 shRNA, and/or infected with retroviruses carrying vector or expression plasmids for PAK1, PAK1Δ15, JMJD6, or JMJD6m." (PMID 29187213, 2017). "JMJD6 deficiency could attenuate the growth of both LLC tumors and B16F10 melanomas by reversing M2-like activation of macrophages, potentially mediated by STAT3/IL-10 signaling." (PMID 37567973, 2023).
melanoma (continued). "However, splicing variations related to cancer have not been reported for any of these genes except PAK1, for which a JMJD6-regulated exon inclusion event altering the PKC domain enhances MAPK signaling in melanoma." (PMID 35581644, 2022). "At later stages of melanoma progression, JMJD6 level is elevated." (PMID 31961032, 2020). "It would be interesting to investigate whether miR-146a levels differ in melanoma developing in kita/Ras (where they are increased according to RNA-Seq data) versus those developing in kita/Ras/Jmjd6." (PMID 30619488, 2018). "Indeed, triple transgenic fish engineered to express a microRNA-resistant Jmjd6 from the onset of melanoma have increased tumor burden, higher infiltration of leukocytes and shorter melanoma-free survival." (PMID 30619488, 2018). "Further work is needed to clarify how Jmjd6 favors melanoma development." (PMID 30619488, 2018). "The dynamic of Jmjd6 levels during progression of melanoma in the zebrafish model suggests that upregulation of the microRNAs targeting Jmjd6 may be part of an anti-cancer response." (PMID 30619488, 2018). "Moreover, JMJD6 expression levels are higher in the samples with HRAS and BRAF mutations compared to samples with wild type HRAS and BRAF, suggesting that JMJD6 is upregulated by RAS signaling in these melanomas." (PMID 30619488, 2018). "We also noticed that Kita/Ras/Jmjd6 melanomas have massive infiltration of leukocytes (L-plastin+ cells), resembling macrophages and neutrophils for their shape, much higher than in to Kita/Ras melanomas." (PMID 30619488, 2018). "However, triple transgenic fish kita/Ras/Jmjd6 developed melanoma at an earlier stage and by 1 month of age, penetrance of melanoma was 95%." (PMID 30619488, 2018). "Thus, the regulation of the MAPK signaling pathway by JMJD6 in melanoma cells supports a role of JMJD6 in the pathogenesis of melanoma." (PMID 29187213, 2017). "We characterized JMJD6 expression in melanoma tissue array by immunohistochemistry analysis." (PMID 29187213, 2017). "As described at the beginning, we found that JMJD6 was up-regulated in melanomas." (PMID 29187213, 2017). "The results showed that overexpression of JMJD6, but not JMJD6m, in melanoma A375 cells was associated with an increased level of the full length PAK1 mRNA and a decreased level of PAK1Δ15 mRNA." (PMID 29187213, 2017). "Indeed, we showed that ectopic expression of JMJD6 promoted the proliferation of melanoma cells, an effect that was dependent on the lysyl hydroxylase activity of JMJD6 and was through the regulation of the alternative splicing of PAK1." (PMID 29187213, 2017). "In the current study, we found that JMJD6 is markedly up-regulated in melanoma, and that high expression of JMJD6 is closely correlated with advanced clinicopathologic stage, aggressiveness, and poor prognosis of melanoma." (PMID 29187213, 2017). "Interestingly, JMJD6 is transcriptionally activated by c-Jun, generating a feedforward loop to drive the development and progression of melanoma." (PMID 29187213, 2017). "We found that the protein level of JMJD6 was significantly higher in melanomas than in normal tissues, and that high expression of JMJD6 was positively correlated with the clinicopathological stage, aggressiveness, and poor prognosis of melanoma." (PMID 29187213, 2017). "We detected a decreased level of the full length PAK1 in JMJD6-depleted melanoma cells." (PMID 29187213, 2017). "Immunohistochemical staining revealed that JMJD6 protein was mainly detected in the nucleus of melanoma cells, and that JMJD6 expression was markedly up-regulated in both primary melanomas and metastatic melanomas, with higher expressions of JMJD6 detected in metastatic melanomas." (PMID 29187213, 2017).
melanoma (continued). "Our study provides evidence that miR-146a is induced by the same MAPK/AKT pathway that sustains melanoma growth at the earliest stages of transformation, when it could exert an anti-melanoma function by repressing Jmjd6 and perhaps also pro-tumoral inflammation." (PMID 30619488, 2018). "The mechanisms through which Jmjd6 promote melanoma progression is still unknown." (PMID 30619488, 2018). "To understand the mechanistic role of JMJD6 in melanoma carcinogenesis, we performed RNA-seq in melanoma cells and found that the alternative splicing of a panel of genes including that encoding for PAK1, a key component of the MAPK signaling pathway, is regulated by JMJD6." (PMID 29187213, 2017). "However, a functional role of JMJD6 in melanoma remains to be explored." (PMID 29187213, 2017). "For instance, JMJD6 enhances MAPK signaling pathway by controlling PAK1 splicing and promotes melanoma cell proliferation, invasion and angiogenesis." (PMID 35359945, 2022). "JMJD6 was found to increase the PAK1-full/PAK1Δ15 ratio, to enhance MAPK signaling and to promote proliferation and invasion of melanoma cells." (PMID 31748572, 2019). "Our results provide a functional link between JMJD6 and the MAPK signaling pathway in the regulation of EMT and metastasis of melanoma." (PMID 29187213, 2017). "Given our observations that JMJD6 influences, via regulation of PAK1 alternative splicing, multiple cellular processes in melanoma cells, understanding the aberrant regulation of JMJD6 in melanomas is of great significance." (PMID 29187213, 2017). "Activated c-Jun transactivates JMJD6, which, in turn, through regulation of the alternative splicing of PAK1, enhances the MAPK signaling and drives melanoma carcinogenesis." (PMID 29187213, 2017). "We demonstrated that JMJD6 enhances the MAPK signaling and promotes multiple cellular processes including melanogenesis, proliferation, invasion, and angiogenesis in melanoma cells." (PMID 29187213, 2017). "To evaluate the role of JMJD6-expressing macrophages in tumor progression, we established two tumor models in WT and Jmjd6+/− mice with subcutaneous injection of LLC lung cancer cells and intravenous injection of B16F10 melanoma cells." (PMID 37567973, 2023). "An example of a high JMJD6 immunostaining in melanoma is shown in comparison to control skin (where JMJD6 is not expressed)." (PMID 30619488, 2018). "Thus, the regulation of PAK1 alternative splicing by JMJD6 would have significant consequences on the MAPK signaling and cellular processes of melanoma cells." (PMID 29187213, 2017). "Given our observations that JMJD6 regulates the alternative splicing of PAK1 and influences the MAPK signaling in melanoma cells, it is conceivable that JMJD6 is also involved in the regulation of EMT and metastasis in melanoma." (PMID 29187213, 2017).
colon carcinoma (12 papers, 2014 to 2023). "We found that the JMJD6 is overexpressed in various human cancers especially in colon cancer, and that high nuclear JMJD6 protein is associated with aggressive clinical behaviors of colon adenocarcinomas." (PMID 24667498, 2014). "For example, interactions between JMJD6 and the Brd4 ET domain are known to drive the progression of neuroblastoma, oral, breast, lung, prostate, and colon cancers." (PMID 37049806, 2023). "Several types of human cancers, especially colon cancer, show an up-regulation of JMJD6 expression, and this over expression positively correlates with the aggressiveness of colon adenocarcinomas." (PMID 36430532, 2022). "Further analysis in colon cancer samples revealed that the higher expression of JMJD6 positively correlated to depth of invasion, lymph node metastasis, advanced tumor node metastasis staging, and poor histologic grading of cancer." (PMID 28587176, 2017). "The identification of JMJD6 as a novel biomarker for colon cancer prognosis and a target for novel therapeutic interventions warrants further study to elucidate the molecular mechanisms of its activity regulation and its biological functions." (PMID 28587176, 2017). "JMJD6 has been reported to be over-expressed in oral, breast, lung, and colon cancers and plays important roles in regulation of transcription through interactions with transcription regulator BRD4, histones, U2AF65, Luc7L3, and SRSF11." (PMID 29176719, 2017). "For colon cancer, elevated JMJD6 expression positively correlated with depth of invasion, lymph node metastasis, and advanced tumor node metastasis stage." (PMID 27081402, 2016). "Elevated levels of JMJD6 protein and mRNA were reported for several tumor types, breast, lung, and colon cancers." (PMID 27081402, 2016). "To further explore the role of JMJD6 in colon carcinogenesis, we collected 90 colon carcinoma samples with paired adjacent normal tissues and performed tissue microarray analysis." (PMID 24667498, 2014). "In these experiments, FLAG-tagged JMJD6 (FLAG-JMJD6) was stably expressed in human colon carcinoma HCT116 cells." (PMID 24667498, 2014). "Our results support the pursuit of JMJD6 as a potential biomarker for colon cancer aggressiveness and a potential target for colon cancer intervention." (PMID 24667498, 2014). "Significantly, the expression of JMJD6 is markedly up-regulated in various types of human cancer especially in colon cancer, and high nuclear JMJD6 protein is strongly correlated with aggressive clinical behaviors of colon adenocarcinomas." (PMID 24667498, 2014). "Importantly, the ET domain is also associated with a variety of cellular proteins such as NSD3 and JMJD6, which are implicated in the development of AML and lung/colon cancers, respectively." (PMID 37049806, 2023). "Although JMJD6 is highly expressed in colon tumors, its role in colon carcinoma is complex." (PMID 35359945, 2022).